TRIM13 (tripartite motif containing 13)
Diseases named in the same sentence as TRIM13 in open-access papers:
TRIM13 is named in the same sentence as 35 diseases in open-access papers, as found by Europe PMC text mining. Sharing a sentence is not in itself a finding about the gene and the disease. The quoted sentences say what the papers report.
B-cell chronic lymphocytic leukemia (3 papers, 2020 to 2024). "TRIM13 was initially identified as a tumor suppressor gene in B-cell CLL, though subsequent studies questioned this observation." (PMID 38397043, 2024).
breast carcinoma (3 papers, 2019 to 2024). "In conclusion, the present work suggests that TRIM13 was lower-expressed in different subtypes of breast cancer compared with normal tissues and was associated with several clinical parameters." (PMID 30837324, 2019). "TRIM13 expression in breast cancer has been positively correlated with metastasis-free survival rates, with higher levels of TRIM13 associated with better prognosis." (PMID 39716068, 2024). "Conversely, SBR grade, NPI index, nodal status, basal-like status, and triple-negative status were negatively related to TRIM13 expression in breast cancer patients in respect to normal individuals." (PMID 30837324, 2019). "More in-depth experiments and clinical trials are needed to validate the value of TRIM13 in breast cancer treatment." (PMID 30837324, 2019). "The co-expression profile of TRIM13 was identified with a large cluster of 8603 genes across 174 cancer samples including 26 breast carcinomas." (PMID 30837324, 2019). "We further investigated the prognostic value of TRIM13 in breast cancer using the PrognoScan and bc-GenExMiner software." (PMID 30837324, 2019). "In the present work, we performed a bioinformatics analysis of the clinical parameters and survival data as it relates to TRIM13 in breast cancer patients by pooling and analyzing several online tools." (PMID 30837324, 2019). "Increased level of TRIM13 (red) was found in brain cancer, lung cancer, and lymphoma; whereas, decreased level of TRIM13 (blue) was observed in esophageal cancer, leukemia, ovarian cancer, and especially breast cancer." (PMID 30837324, 2019). "ER-positive or PR-positive breast cancer patients tended to express higher TRIM13 gene compared with ER-negative or PR-negative patients." (PMID 30837324, 2019). "The SBR grade and NPI index are two accepted prognostic factors for breast cancer; more advanced SBR grade and NPI index were associated with lower TRIM13 level." (PMID 30837324, 2019). "To further investigate the role of TRIM13 in breast cancer prognosis, we used the bc-GenExMiner software to verify our findings." (PMID 30837324, 2019). "It suggested that TRIM13 is a promising marker for breast cancer prognosis." (PMID 39667820, 2024). "TRIM13 could be adopted as a promising predictive biomarker for prognosis of breast cancer with co-expressed RAB11FIP2 gene." (PMID 30837324, 2019). "However, the significance of TRIM13 expression in the development and prognosis of breast cancer remains largely unclear." (PMID 30837324, 2019). "In the present study, we performed a bioinformatics analysis of the clinical parameters and survival data as it relates to TRIM13 in breast cancer patients using several large online databases in order to evaluate the prognostic significance of TRIM13 gene in breast cancer treatment." (PMID 30837324, 2019). "Breast cancer patients with increased TRIM13 level (red) presented better relapse free survival." (PMID 30837324, 2019). "However, the prognostic significance of TRIM13 gene in breast cancer treatment remains largely unclear." (PMID 30837324, 2019). "After analyzing breast cancer patient data in the TCGA database using the UCSC Xena web-based tool, we also confirmed a positive correlation between TRIM13 and RAB11FIP2 expression, as shown in the heat map." (PMID 30837324, 2019). "Moreover, TRIM13 was significantly elevated in non-triple-negative and non-basal-like breast cancer patients with respect to triple-negative and basal-like breast cancer patients." (PMID 30837324, 2019).
non-small cell lung carcinoma (3 papers, 2021 to 2022). A group of at least three distinct histological types of lung cancer, including non-small cell squamous cell carcinoma, adenocarcinoma, and large cell carcinoma. "They found that compared with non-cancerous tissues and normal bronchial epithelial cell lines, non-small cell lung cancer tissues and cell lines have reduced TRIM13 mRNA and protein expression." (PMID 35847032, 2022). "In contrast to our findings, two previous studies found that TRIM13, another TRIM protein, inactivated NF-κB in both RCC and non-small-cell lung carcinoma." (PMID 34284744, 2021).
viral infection (3 papers, 2022 to 2025). "Further to its ability to dampen inflammation in metabolic stress models, TRIM13 (class XI) also curbs NF-κB signaling during viral infection, offering a more permissive environment for replication." (PMID 38115822, 2023). "This is supported by a whole-body Trim13–/– mouse model that results in reduced type I interferon (IFN) signaling and curbs the ability of macrophages to respond to viral infection (see Section 6 “The role of TRIMs in fighting viruses in the brain”)." (PMID 38115822, 2023).
atherosclerosis (2 papers, 2024 to 2025). A disease characterized by the build-up of fatty material and calcium deposition in the arterial wall resulting in partial or complete occlusion of the arterial lumen. "Recent studies have discovered that during atherosclerosis, the expression of Tripartite Motif Containing 13 (TRIM13) in macrophages increases." (PMID 41425976, 2025). "We also found that genetic deletion of TRIM13 ameliorates diet-induced atherosclerosis via restoration of cholesterol efflux and inhibition of cholesterol uptake and foam cell formation." (PMID 38537695, 2024). "To validate the translational relevance of the findings obtained in the mouse model of atherosclerosis in humans, we studied the effect of IL-1β on the expression of TRIM13 and its downstream effectors in human cells." (PMID 38537695, 2024). "All these observations reveal for the first time that TRIM13 by affecting cholesterol efflux and oxLDL uptake plays a key role in diet-induced atherosclerosis." (PMID 38537695, 2024). "Together these results show that TRIM13 plays a crucial role in diet-induced atherosclerosis, and that it could be a potential therapeutic target against this vascular lesion." (PMID 38537695, 2024). "Since the role of MARCH6, GP78, and IDOL in the regulation of cholesterol homeostasis and/or atherosclerosis has been studied previously, and very little is known about the role of TRIM13 in vascular diseases, we then focused our attention on this E3 ubiquitin ligase." (PMID 38537695, 2024). "Together, these observations reveal for the first time that TRIM13 plays a crucial role in diet-induced atherosclerosis, and that it could be a potential drug target against this vascular lesion." (PMID 38537695, 2024). "It should be also pointed out that as TRIM13 was induced by both WD and IL-1β in peritoneal macrophages and MASMCs affecting cholesterol efflux and oxLDL uptake, it is likely that both these cell types are contributing to TRIM13-mediated foam cell formation and atherosclerosis." (PMID 38537695, 2024). "To extrapolate the translational relevance of our novel findings observed in mouse model system to human atherosclerosis, first, we found induction of TRIM13 and its downstream effectors in HASMCs and PMA-differentiated THP1 cells in response to proatherogenic cue, IL-1β." (PMID 38537695, 2024). "Thus, all these findings clearly demonstrate a role for TRIM13 in diet-induced atherosclerosis." (PMID 38537695, 2024). "Here, we report that tripartite motif-containing protein 13 (TRIM13), a RING-type E3 ubiquitin ligase, plays a role in arterial lipid accumulation leading to atherosclerosis." (PMID 38537695, 2024).
leukemia (2 papers, 2019 to 2024). A malignant (clonal) hematologic disorder, involving hematopoietic stem cells and characterized by the presence of primitive or atypical myeloid or lymphoid cells in the bone marrow and the blood. "TRIM13, a member of the TRIM family, has been reported to play a role in diverse cellular functions such as cell growth, immunity, and tumorigenesis including lipoma, leukemia, and myeloma." (PMID 30837324, 2019).
lymphoma (2 papers, 2019 to 2024). A malignant (clonal) proliferation of B- lymphocytes or T- lymphocytes which involves the lymph nodes, bone marrow and/or extranodal sites. "Conversely, despite the suggested involvement in lymphoma development and the progression of TRIM11, TRIM13, TRIM19, TRIM32, TRIM35, TRIM65, data on their possible function regarding NLRP3 inflammasome regulation are lacking." (PMID 38397043, 2024).
Insulin resistance (1 paper, 2022). Increased resistance towards insulin, that is, diminished effectiveness of insulin in reducing blood glucose levels. "Brain-specific deletion of TRIM13 in mice promoted HFD-induced metabolic disorder, hypothalamic insulin resistance and systematic inflammatory response." (PMID 36139694, 2022). "In vitro analysis of TRIM13 knockout glial cells showed an enhanced palmitate (PAL)-induced inflammatory response by accelerating the NF-κB signal, which then contributed to the insulin resistance in the isolated primary neuron." (PMID 36139694, 2022).
kidney cancer (1 paper, 2025). Primary or metastatic malignant neoplasm involving the kidney. "TRIM7, TRIM13, and TRIM26 regulate the PI3K/AKT/mTOR pathway as tumor suppressors in kidney cancers." (PMID 40723250, 2025).
osteosarcoma (1 paper, 2024). A usually aggressive malignant bone-forming mesenchymal neoplasm, predominantly affecting adolescents and young adults. "Then, investigating the role of E3 ligases such as CHIP, Tripartite Motif Protein 13 (TRIM13), or Zinc and Ring Finger 1 (ZNFR1) in osteosarcoma could uncover new mechanisms of cancer growth that could be targeted for treatment purposes." (PMID 38534381, 2024).
renal cell carcinoma (1 paper, 2024). "For example, TRIM13 expression is significantly reduced in renal cell carcinoma tissues, and its ectopic expression decreases the migration and invasion of renal cell carcinoma cells." (PMID 39716068, 2024).
Sepsis (1 paper, 2025). Sepsis is defined as life-threatening organ dysfunction caused by a dysregulated host response to infection. "Restricting TRIM13 sustains DC immunostimulatory property, counteracts sepsis-induced immunosuppression, and improves survival outcomes." (PMID 41647935, 2025).
cancer (12 papers, 2017 to 2025). A tumor composed of atypical neoplastic, often pleomorphic cells that invade other tissues. "According to their research, NEMO, a substrate of TRIM13, plays a notable role in the NF-κB signaling pathway, which regulates the expression of several inflammatory cytokines and is associated with cancer." (PMID 35847032, 2022). "It was previously reported that TRIM13 ubiquitinates and degrades Nur77, a nuclear receptor, in cancer cells." (PMID 38537695, 2024). "These implicate that S-scores and N-scores can allow one to find another type of biomarkers such as EXT1, PTCH1, KLK10, APC, TRIM13 that have strong information sensitive to early cancer." (PMID 33580150, 2021). "We first measured the expression of TRIM13 gene in 20 common types of cancer and compared its level to normal tissues using the Oncomine online database." (PMID 30837324, 2019). "TRIM13 negatively regulates the NF-κB signaling pathway, and its dysregulation may contribute to cancer pathogenesis." (PMID 39716068, 2024). "Ultimately, TRIM13 inhibits the proliferation of cancer cells." (PMID 35847032, 2022). "This study suggests that TRIM13 can promote tumor cell apoptosis, which indicates that TRIM13 may be deleted or inactivated in some cancer tissues and cell lines." (PMID 35847032, 2022). "TRIM13 is a tumor suppressor gene whose deletion is common in various malignant tumors." (PMID 35847032, 2022). "Taken together, these findings suggest that TRIM13 may not only function as a tumor suppressor, but also as a potential predictive biomarker for prognosis of cancer." (PMID 30837324, 2019). "In NSCLC cancer tissues, RBM15 expression was positively correlated with KLF1 and negatively correlated with TRIM13 (p < 0.01)." (PMID 39716068, 2024). "Currently, our study demonstrates that TRIM13 downregulation promotes NSCLC cancer cell proliferation, increases clone numbers, enhances lung and liver metastasis, and boosts cancer cell invasion and migration." (PMID 39716068, 2024). "LATS2, MCC, DCC, RHOB, TRIM13, LIMD1, and GPC3 also strongly and positively regulated gene down-expression in cancer." (PMID 33580150, 2021). "First, TBRG1, PICH1, NBL1, TRIM13 and APC did not impact gene up-expression in cancer." (PMID 33580150, 2021).
tumor (11 papers, 2018 to 2025). "Analysis of the data revealed that TRIM13 was significantly downregulated in LC tumor tissues compared with normal tissues." (PMID 39667820, 2024). "We first detected the mRNA expression level of TRIM13 in LC tumor tissues and adjacent normal tissues by qRT‐PCR." (PMID 39667820, 2024). "As a ubiquitin ligase, TRIM13 regulates the protein levels of downstream factors and functions as a tumor suppressor through ubiquitination." (PMID 39716068, 2024). "This study confirmed by western blot and IHC analysis that TRIM13 was significantly underexpressed in LC tumor tissues and cell lines." (PMID 39667820, 2024). "We found that TRIM13 overexpression significantly inhibited the increase in tumor volume and weight in mice compared to the LV‐NC group." (PMID 39667820, 2024). "The study demonstrated TRIM13 was identified as a novel tumor suppressor gene of LC and its overexpression suppressed LC progression in vitro and in vivo." (PMID 39667820, 2024). "TRIM13, for example, is an E3 ubiquitin ligase that has been found to be de-regulated in several tumor types, including B-cell chronic lymphocytic leukemia, multiple myeloma and non-small-cell lung carcinoma." (PMID 36769122, 2023). "While TRIM13 was first identified as a candidate tumour suppressor in B-CLL, there are conflicting reports on its relevance." (PMID 29110249, 2018). "TRIM13 was initially identified as a putative tumour suppressor gene in B cell chronic lymphocytic leukaemia (B-CLL)." (PMID 29110249, 2018). "However, the detailed mechanisms of how TRIM13 exerts its tumor-suppressive effects, particularly in the context of m6A modification, remain underexplored." (PMID 39716068, 2024). "In LUAD, TRIM13 inhibits tumor growth by enhancing apoptosis and oxidative stress." (PMID 39716068, 2024). "In contrast, KLF1 overexpression and TRIM13 downregulation accelerated tumor growth (p < 0.05)." (PMID 39716068, 2024). "Next, we hypothesized that TRIM13 might act as a tumor suppressor gene by ubiquitinating and degrading RPS27A, ultimately attenuating the proliferation and metastasis of LC cells." (PMID 39667820, 2024). "Besides, immunohistochemistry (IHC) analysis also confirmed the downregulation of TRIM13 in LC tumor tissues." (PMID 39667820, 2024). "In addition, the inhibitory effects of TRIM13 overexpression on tumor volume and weight were partially blocked by RPS27A overexpression." (PMID 39667820, 2024). "Furthermore, upregulation of TRIM13 significantly inhibited the proliferation and metastasis of LC cells in vitro, and attenuated tumor growth in mice in vivo." (PMID 39667820, 2024). "There is growing evidence to support the tumor suppressor role of TRIM13." (PMID 39716068, 2024). "Finally, in vivo experiments revealed that RPS27A overexpression partially blocked the inhibitory effect of TRIM13 overexpression on tumor growth in LC xenograft mice." (PMID 39667820, 2024). "TRIM13 can not only promote tumor cell apoptosis but also regulate cell proliferation." (PMID 35847032, 2022). "Additionally, TRIM13 has been found to regulate the activation of caspase-8 to induce autophagy, leading to tumor cell death in tumors." (PMID 32984318, 2020). "Analysis of tumor tissues showed significant downregulation of RBM15, KLF1, and ANXA8, along with reduced m6A content (p < 0.01), while TRIM13 expression was increased (p < 0.01) in the sh-RBM15 group compared to the sh-NC group." (PMID 39716068, 2024). "Compared to that in adjacent normal tissues, we found significantly lower TRIM1, 2, and 26 and significantly higher TRIM13, 27, 55, 47, and 35 expressions in KIRC tumor." (PMID 35371994, 2022). "Furthermore, overexpression of TRIM13 in NSCLC has been shown to inactivate the NF-κB pathway, increase cleaved caspase-3 levels, inhibit tumor growth, and induce apoptosis in NSCLC cells." (PMID 39716068, 2024).
tumor (continued). "Furthermore, our experiments demonstrated that RBM15 downregulation significantly inhibited lung and liver metastasis of tumor cells, while KLF1 overexpression and TRIM13 downregulation significantly promoted lung and liver metastasis (p < 0.05)." (PMID 39716068, 2024). "Similarly, TRIM13 expression is downregulated in NSCLC, and its overexpression suppresses tumor growth and induces cell apoptosis." (PMID 39716068, 2024). "Although more TRIM13, 35, and 55 mRNA was expressed in KIRC tumor tissues, this might favor a better clinical prognosis for patients with KIRC." (PMID 35371994, 2022).
infection (1 paper, 2021). The state of being infected such as from the introduction of a foreign agent such as serum, vaccine, antigenic substance or organism. "TRIM13 could initiate the innate immune response in the early stage of infection by positively regulating the RIG-I pathway." (PMID 33791238, 2021). "Although the precise molecular mechanism hasn’t been clarified, the possible reasons are as follows: Firstly, The dual-directional regulation of TRIM13 on RIGI and MDA5 may be related to the time course of infection." (PMID 33791238, 2021). "TRIM13 may inhibit the effect of persistent activation of MDA5 on RIG I by negatively regulating the MDA5 pathway, which represses excessive immune response and avoids immunopathological damage in the late stage of infection." (PMID 33791238, 2021).
TRIM13 also shares sentences with these, for which no sentence is quoted: esophageal cancer (2 papers); lung carcinoma (2); ovarian carcinoma (2); brain cancer (1); COVID-19 (1); developmental verbal dyspraxia (1); diabetes mellitus (1); ductal breast carcinoma in situ (1); head and neck squamous cell carcinoma (1); Hypercholesterolemia (1); invasive breast carcinoma (1); invasive ductal breast carcinoma (1); invasive lobular breast carcinoma (1); lipoma (1); lung adenocarcinoma (1); medullary carcinoma (1); mucinous carcinoma (1); myeloma (1); tuberculosis (1); tubular breast carcinoma (1).